TMIGD2 (transmembrane and immunoglobulin domain containing 2)
Diseases named in the same sentence as TMIGD2 in open-access papers (continued):
Sharing a sentence is not in itself a finding about the gene and the disease.
tumor (continued). "Subsequently, all factors identified from the univariate analysis were included in the multivariate analysis: age, PDCD1/CD27 ratio, PDCD1/TNFSF4 ratio, IDO1/TMIGD2 ratio, IDO1/TNFSF4 ratio, neoadjuvant treatment, initial weight of tumor, ER status, PR status, HER2 status, and TNM stage." (PMID 40061889, 2025). "The results showed that m6Ascore was negatively correlated with the expression of TMIGD2, TNFRSF18, TNFRSF25, TNFRSF4, TNFRSF8, and NRP1, indicating that the poor prognosis of high-m6Ascore patients might be due to the tumor immunosuppressive microenvironment." (PMID 36313417, 2022). "Therefore, it can be speculated that CD27, PDCD1, TMIGD2 and TNFRSF25 may participate in tumour immunity by regulating IMCPs." (PMID 37849388, 2023). "Additionally, neither immune nor tumor cells with wild-type or muted IDH-1 displayed statistical differences in TMIGD2 expression (p= 0.0685; 0.1592)." (PMID 37261362, 2023). "However, TMIGD2 was reported to be expressed on naïve T cells but not on other immune cells, and T-cell infiltration in the tumour sites comprises T effector cells derived from naïve T cells activated by antigen-presenting cells in the lymph node." (PMID 33962626, 2021). "Therefore, CD27, PDCD1, TMIGD2 and TNFRSF25 may participate in tumour immunity by regulating IMCPs." (PMID 37849388, 2023). "Moreover, neither HHLA2 expression nor TMIGD2 expression was related to tumor size." (PMID 31089395, 2019).
cancer (26 papers, 2016 to 2025). A tumor composed of atypical neoplastic, often pleomorphic cells that invade other tissues. "Targeting the HHLA2/KIR3DL3/TMIGD2 pathway, which we intend to explore in the future work, may be beneficial for cancer treatment and improve clinicopathological conditions such as survival." (PMID 38731979, 2024). "Some researches have demonstrated that HHLA2 promotes T-lymphocyte proliferation and cytokine release when interacting with the TMIGD2 receptor, which suggests that HHLA2 and TMIGD2 function through a co-stimulatory pathway to stimulate T cells to eliminate cancer cells." (PMID 33962626, 2021). "The discovery of TMIGD2 (Transmembrane and Immunoglobulin Domain Containing 2) as an immuno-stimulatory receptor, constitutively expressed on naive T cells and most natural killer (NK) cells, has emerged as an attractive immunotherapy target in a variety of cancers." (PMID 37261362, 2023). "Since immune checkpoint inhibitors (ICIs) have been a prominent topic in cancer treatment, the expression of eight ICIs (LAG3, HAVCR2, CD27, TNFRSF14, CTLA4, TMIGD2, TIGIT, and PDCD1LG2) were analyzed between groups in the study." (PMID 37405988, 2023). "Transmembrane and immunoglobulin domain-containing 2 (TMIGD2) serves as the receptor for HHLA2, and the level of this protein is limited in normal tissues but high in many malignant carcinomas." (PMID 32265918, 2020).
TMIGD2 also shares sentences with these, for which no sentence is quoted: melanoma (3 papers); cervical cancer (2); osteosarcoma (2); skin melanoma (2); acute erythroid leukemia (1); acute promyelocytic leukemia (1); adenoma (1); atherosclerosis (1); breast carcinoma (1); cardiovascular diseases (1); colorectal adenocarcinoma (1); colorectal tumor (1); COVID-19 (1); endothelial dysfunction (1); hematologic malignancies (1); hepatoma (1); infection (1); lung carcinoma (1); lymphoma (1); oligoastrocytoma (1); oligodendroglioma (1); pancreatic cancer (1); pancreatic ductal adenocarcinoma (1); Sepsis (1); small cell lung carcinoma (1); thyroid cancer (1); thyroid tumor (1); tubular adenoma (1).